OSM (oncostatin M)
Description:
Functions as a cytokine that uses both type I OSM receptor (heterodimers composed of LIFR and IL6ST) and type II OSM receptor (heterodimers composed of OSMR and IL6ST). Functionally, regulates many processes including cell proliferation, cell differentiation, cytokine production. Mechanistically, low affinity ligand binding to IL6ST/gp130, induces heterodimerization with LIFR or OSMR, activating JAK tyrosine kinases (JAK1 or JAK2 and to a lesser extent TYK2) bound to their intracellular domains. These kinases subsequently phosphorylate IL6ST/gp130 and LIFR or OSMR. The tyrosine phosphorylated signaling receptors serve in turn as docking sites for recruitment and activation of STAT3. The type II OSM complex receptor is also able in addition to STAT3 to recruit STAT5B. Moreover, the type II OSM complex receptor recruits SHC1 through OSMR in a JAK1 mediated phosphotyrosine-dependent manner, leading to SHC1 association with GRB2 and downstream activation of the Ras/Raf/MAPK pathway.
Synonyms: MGC20461
Tractability: Antibody: its Gene Ontology location is reachable by antibodies, with high confidence; UniProt places it where antibodies can reach, with medium confidence; UniProt predicts a signal peptide or a membrane-spanning region.
Gene: Protein-coding gene on chromosome 22 (30,262,829 to 30,266,851, reverse strand). Ensembl gene ENSG00000099985.
Subcellular location: Secreted
Pathways (Reactome):
Immune System: IL-6-type cytokine receptor ligand interactions; Interleukin-4 and Interleukin-13 signaling
Gene Ontology:
Molecular function: cytokine activity; growth factor activity; oncostatin-M receptor binding; protein binding
Biological process: cell population proliferation; negative regulation of hormone secretion; oncostatin-M-mediated signaling pathway; positive regulation of cell population proliferation; positive regulation of inflammatory response; positive regulation of interleukin-17 production; positive regulation of MAPK cascade; positive regulation of peptidyl-serine phosphorylation; positive regulation of peptidyl-tyrosine phosphorylation; positive regulation of phosphatidylinositol 3-kinase/protein kinase B signal transduction; positive regulation of transcription by RNA polymerase II; positive regulation of tyrosine phosphorylation of STAT protein; negative regulation of cell population proliferation; positive regulation of acute inflammatory response; regulation of hematopoietic stem cell differentiation; immune response; regulation of cell communication; regulation of signaling
Cellular component: extracellular region
Genetic constraint (gnomAD): Loss-of-function variants: 2 observed, 6.86 expected, observed/expected ratio (o/e) 0.29, 90% interval 0.12 to 0.92. That is too few expected variants to judge how well the gene tolerates losing a copy. Missense variants: 324 observed, 332.03 expected, observed/expected ratio (o/e) 0.98, 90% interval 0.89 to 1.07. Synonymous variants: 135 observed, 142.58 expected, observed/expected ratio (o/e) 0.95, 90% interval 0.82 to 1.09.
Homologues: Orthologues: chimpanzee OSM (99% identical), macaque OSM (92% identical), pig OSM (62% identical), dog OSM (61% identical), mouse Osm (46% identical), rat Osm (42% identical).
Diseases named in the same sentence as OSM in open-access papers:
OSM is named in the same sentence as 230 diseases in open-access papers, as found by Europe PMC text mining. Sharing a sentence is not in itself a finding about the gene and the disease. The quoted sentences say what the papers report.
breast carcinoma (40 papers, 2010 to 2025). "In turn, in vivo, the cancer-associated adipose tissue secretes oncostatin M (OSM) contributing to the breast cancer progression." (PMID 40136652, 2025). "Evidence has implicated OSM as a myokine capable of inhibiting several cancer types including melanoma, lung cancer, and breast cancer." (PMID 39123444, 2024). "TIMER analysis showed that OSMR mRNA expression significantly correlates with fibroblast enrichment in human breast cancer, while OSM mRNA levels show the most significant associations with myeloid macrophage and neutrophil populations." (PMID 35192545, 2022). "Bioactivity of the rhOSM was comparable to commercially available recombinant human OSM (chOSM) in human breast cancer cells as determined by an enzyme-linked immunosorbent assay (ELISA), which detected phosphorylation of STAT3." (PMID 34376712, 2021). "OSM was reported to be expressed by neutrophils cocultured with breast cancer cells and to promote phenotypic changes associated with mesenchymal and stem cell–like differentiation in breast cancer." (PMID 38236642, 2024). "While OSM has historically been identified as an inhibitor of breast cancer proliferation, overexpression of OSM and OSMRβ has been linked to decreased overall survival, decreased reoccurrence-free survival and decreased metastasis free survival in breast cancer patients." (PMID 37841259, 2023). "Due to the range of literature regarding OSM involvement at different stages of breast cancer, further research would be required to identify the impact of Anti-OSM, specifically, on breast cancer at different stages of disease." (PMID 39123444, 2024). "Tumor-educated Gr1+CD11b+ cells convert low metastatic SCA1- breast cancer cells into highly metastatic SCA1+ cells via secreted OSM and IL6 and JAK signaling." (PMID 38236642, 2024). "It has been reported that the expression of OSM increases in neutrophils in response to TCM isolated from an aggressive breast cancer cell line and promotes cancer cell detachment and invasion." (PMID 37682817, 2023). "Despite the initial identification of OSM as a tumor suppressor, a pro-inflammatory role of OSM has been reported in colon cancer, breast cancer, pancreatic cancer, myeloma, brain tumors, chronic lymphocytic leukemia, hepatoblastoma and COVID-191,3,8." (PMID 37961653, 2023). "In this review, we summarize the role of the IL-6 cytokine family—specifically IL-6 itself, LIF, OSM, and IL-11—as relevant players during breast cancer progression." (PMID 35163731, 2022). "In addition, we showed that core fucosylation of integrin αvβ5 or IL6ST might be crucial for breast cancer cell adhesion to vitronectin or enhanced cellular signaling to interleukin 6 and oncostatin M, two cytokines implicated in the breast cancer epithelial–mesenchymal transition and metastasis." (PMID 35303925, 2022). "Aberrant expression of OSM promoted cellular invasion and induced mesenchymal phenotype in many solid tumors including osteosarcoma, gliomas and breast cancer." (PMID 34037532, 2021). "Further examination revealed that the myokine oncostatin M is involved in exercise-induced apoptosis in breast cancer cells." (PMID 34359731, 2021). "That same study also noted that recombinant OSM potently suppressed the ER protein and mRNA expression in vitro and that loss of ER expression was necessary for OSM-mediated signal transduction and migratory effects in ER+ MCF7 and T47D breast cancer cells." (PMID 32023849, 2020). "While the predominant signaling pathway activated by the gp130 cytokines is the JAK-STAT signaling axis, OSM has been shown to suppress ER protein and mRNA expression in ER+ breast cancer cells through the MAPK-ERK pathway." (PMID 32023849, 2020). "In the context of OSM/OSMR signaling, high levels of OSM and OSMR mRNA expression were associated with low expression of ESR1 (ER) and ER-regulated genes in a breast cancer gene expression data set." (PMID 32023849, 2020).
breast carcinoma (continued). "OSM and IL-6 have previously been implicated in the production of proangiogenic factors such as VEGF to promote breast cancer progression and reduced patient survival." (PMID 31007849, 2019). "Because it has been demonstrated that OSM functions in normal bone homeostasis, this work suggests an important role for OSM during postintravasation breast cancer metastasis to bone and subsequent bone destruction." (PMID 29898744, 2018). "Histology performed on tissues from mice injected with parental 4T1.2 cells using an antimouse OSM antibody showed strong OSM expression in the primary mammary tumor, as well as some background expression in the normal breast connective tissue." (PMID 29898744, 2018). "In breast cancer, neutrophil-derived oncostatin M signals human breast cancer cells to secrete VEGF and increases breast cancer cells’ detachment and invasiveness." (PMID 27198767, 2016). "In agreement with this IHC analysis of human breast cancer specimen also revealed upregulated levels of Oncostatin M and Eotaxin in the hypoxic area which in turn coincided with higher number of CD206 expressing M2-macrophages." (PMID 25051364, 2014). "HB-EGF and OSM are co-expressed by TAM in breast carcinoma patients, and plasma levels of both ligands correlate strongly." (PMID 23597096, 2013). "For instance, breast cancer cells have been shown to stimulate oncostatin M release from neutrophils, which in turn increased invasive potential of the breast cancer cells." (PMID 24276377, 2013). "Breast cancer cells secrete much higher level of M-CSF, OSM, MIP-2/CXCL-2, MMP-9 and TIMP-1 than ES cells, which are factors correlated with tumor metastasis." (PMID 22174624, 2011). "We hypothesized that OSM is involved in physical activity-induced breast cancer prevention, and that OSM antibody (Anti-OSM) administration would mitigate the effect of physical activity in a rat model of mammary carcinoma." (PMID 39123444, 2024). "Future studies may examine oncostatin M and other proteins produced by exercising muscles for their potential role in breast cancer prevention." (PMID 39123444, 2024). "However, a pro-tumorigenic role of OSM has also been reported in breast cancer or pancreatic cancer." (PMID 39683503, 2024). "TAN’s co-cultured with human breast cancer cell lines have also been shown to increase TAN-mediated secretion of OSM throughout the tumor microenvironment, which in turn leads to increased secretion of the pro-angiogenic factor VEGF from human breast cancer cells." (PMID 37841259, 2023). "Stromal OSM/OSMRβ has recently been shown to play a distinct role in breast cancer progression." (PMID 37841259, 2023). "OSM has also been shown to promote secretion of IL-6 in ERα- cells and not in ERα+ cells, further suggesting that OSM plays unique roles in ERα+ versus ERα- breast cancer." (PMID 37841259, 2023). "Studies have shown that the secretion of various factors, including leptin, insulin‐like growth factor 1, and oncostatin M, from hASCs could promote breast cancer." (PMID 35600659, 2022). "Furthermore, high expression of OSM and its receptor (OSMR) was associated with poor prognosis for breast cancer patients." (PMID 35163731, 2022). "Here, we discovered that the cytokine oncostatin M (OSM) acts as a central regulator of the crosstalk between immune cells, CAFs, and cancer cells, and that these immune-stromal–cancer cell interactions favor breast cancer progression and metastasis." (PMID 35192545, 2022). "Moreover, increased expression of both OSM and the OSM receptor (OSMRβ) have been correlated with increased recurrence of tumors and decreased survival in breast cancer patients." (PMID 34376712, 2021). "Together, these results suggest that OSM protein levels are higher in the earlier stages of breast cancer and that tumor cell-produced OSM may be important in autocrine signaling for the promotion of tumor progression." (PMID 29898744, 2018).
breast carcinoma (continued). "Thus our results clearly demonstrate the role of Eotaxin and Oncostatin M as key mediators being released by hypoxic breast cancer cells for chemoattracting and polarizing macrophages towards a M2-skewed phenotype with a pro-angiogenic function." (PMID 25051364, 2014). "Breast tumor cells and ES cells secrete cytokines and chemokines to their microenvironment, however, breast cancer cells secrete a significantly higher level of soluble factors, which is correlated with tumor metastasis (e.g., M-CSF, OSM, MIP-2/CXCL-2, MMP-9, TIMP-1)." (PMID 22174624, 2011). "OSM may also play a role in skeletal metastasis of breast cancer." (PMID 35328707, 2022). "Therefore, these authors proposed that early treatment of breast cancer patients with OSM inhibitors may prevent metastatic progression." (PMID 35163731, 2022). "Our data suggest that OSM–OSMR interactions may also be responsible for inducing TGM2 in other cell types, such as breast cancer cells, in which OSM promotes cell motility and metastatic behaviour and TGM2 has been associated with migration, invasion and metastasis 29–33." (PMID 23765377, 2013). "In breast cancer, TAN-derived oncostatin M (OSM) activates the JAK-STAT pathway in tumor cells, promoting VEGF expression and angiogenesis." (PMID 40805288, 2025). "For example, we discovered that oncostatin M (OSM), a member of IL6 subfamily, drives breast cancer progression by modulation of the TME and the activation of cytokine‐mediated protumour inflammatory networks." (PMID 39918251, 2025). "The muscle-derived cytokine (myokine), oncostatin M (OSM), has been shown to decrease breast cancer cell proliferation." (PMID 39123444, 2024). "Available research shows that among myokines, aerobic exercise releases oncostatin M (OSM), thus resulting in lower tumor volume in breast cancer mice." (PMID 36612320, 2023). "In breast cancer, the most studied members of this family are interleukin-6 (IL-6), leukemia inhibitory factor (LIF), oncostatin M (OSM), and interleukin-11 (IL-11)." (PMID 35163731, 2022). "Although this interaction is not known to regulate COL11A1 function, binding, or signaling, OSM has been noted to be immobilized to type XI collagen induced signal transducer and activator of transcription (STAT) signaling in the breast cancer cell line T47D." (PMID 35847935, 2022). "Oncostatin M (OSM), an inflammatory cytokine, has also been shown to bind to collagen type XI after being deposited by neutrophils in MDA-MB-231 breast cancer cell-derived matrices in vitro." (PMID 35847935, 2022). "Further, the myokines oncostatin M (OSM) and Irisin were shown to decrease breast cancer cell migration and viability in vitro." (PMID 33806053, 2021). "Among the pathways in cancer indicated by KEGG analysis, the upregulated miR-222 was involved in pivotal pathways, such as OSM, IL-6 and ERK/MAPK signaling pathways in breast cancer, known pathways to be activated in IBC." (PMID 33901254, 2021). "Oncostatin M (OSM), an inflammatory cytokine, has also been shown to bind to collagen type XI after being deposited by neutrophils to MDA-MB-231 breast cancer cell-derived matrices in vitro." (PMID 33668097, 2021). "It has been previously established that LIFR expression on breast cancer cells promotes tumor dormancy in the bone marrow and that several of the gp130 cytokines (LIF, OSM, and CNTF) are able to signal through LIFR." (PMID 32023849, 2020). "Adipose stroma cell-derived IL-6, oncostatin M (OSM), and C-C motif chemokine ligand 2 (CCL2) have been shown to promote breast cancer cell proliferation, migration and invasion." (PMID 32242230, 2020). "Cytokines such as interleukin-6 (IL-6), oncostatin M (OSM), and interleukin-1 beta (IL-1β) promote the development of both acute and chronic inflammation while promoting in vitro metrics of breast cancer metastasis." (PMID 31007849, 2019).
breast carcinoma (continued). "In breast cancer (DCIS), both oncostatin M (OSM) and interleukin-6 (IL-6) have been proposed to regulate the expression and activity of S100A7 by regulating PI3K, STAT3 and Erk signaling." (PMID 20689826, 2010). "Oncostatin M (OSM) is a proinflammatory cytokine implicatedininflammatory diseases and multiple cancers, especially breast cancer.To date, no federally approved anti-OSM therapeutics exist." (PMID 40747931, 2025). "Despite the body of literature defining the numerous roles of the gp130 cytokine family members, there are still mechanisms of action that remain unknown, particularly with regards to the contradictory effects of OSM and LIF on breast cancer cells." (PMID 32023849, 2020). "Moreover, the in vivo knockdown of oncostatin M (OSM), a pleiotropic IL-6 family cytokine, seems to decrease breast cancer bone metastasis." (PMID 31847214, 2019). "However, OSM can signal through both LIFR and OSMR to induce downstream signaling, and the function of OSM:LIFR and OSM:OSMR signaling in breast cancer cells has not been fully explored." (PMID 32023849, 2020). "To determine the in vivo role of OSM in breast cancer metastasis to the lung, we used three orthotopic breast cancer mouse models, including a syngeneic 4T1.2 mouse mammary cancer model, the MDA-MB-231 human breast cancer xenograft model, and an OSM-knockout (OSM-KO) mouse model." (PMID 29898744, 2018). "Furthermore, OSM and OSMR are upregulated in response to STAT3 activation and the signaling triggered by this cytokine promoted the expression of metalloproteinases MMP3, MMP12, and MMP14, that are relevant for remodeling normal mammary tissue, but would also facilitate mammary tumor invasiveness." (PMID 35163731, 2022). "Moreover, induction of oncostatin M was detected in cancer-stimulated ASCs, whereas the downstream S100A7 binding proteins/receptor for advanced glycation endproducts were significantly upregulated in correspondence with S100A7 expression in breast cancer cells after coculture with ASCs." (PMID 28629450, 2017). "While OSM, LIF, and IL-6 can induce STAT3, AKT, and ERK signaling in breast cancer cells, in the absence of studies using combinations of STAT3, AKT, and ERK inhibitors, it is difficult to determine which is the dominant downstream mediator." (PMID 32023849, 2020).